NOTCH1 (notch receptor 1)
Diseases named in the same sentence as NOTCH1 in open-access papers (continued):
Sharing a sentence is not in itself a finding about the gene and the disease.
prion disease (3 papers, 2010 to 2022). A transmissible disease that is caused by a protein that is able to induce abnormal folding of normal cellular proteins, leading to characteristic spongiform brain changes, which are associated with neuronal loss without an inflammatory response. "The first evidence that the Notch-1 pathway might be important in prion disease was the finding that the formation of NICD is associated with rPrPSc accumulation in neocortical synaptosomes." (PMID 20205843, 2010). "Activation of Notch-1 is responsible for neuronal process shrinkage and dendritic atrophy in prion disease and can be rescued by inhibition of North-1 activation." (PMID 22952817, 2012). "The hypothesis that the Notch-1 intracellular domain, NICD, is involved in prion disease was tested by treating prion-infected mice with the γ-secretase inhibitor (GSI) LY411575, with quinacrine (Qa), and with the combination of GSI + Qa." (PMID 20205843, 2010).
prostate (3 papers, 2010 to 2024). "Aberrant activation of Notch1 signaling alone only leads to hyperplasia and is insufficient to drive prostate carcinogenesis." (PMID 38538986, 2024). "In the prostate, Notch-1 is a marker for SC/progenitor cells, is required for normal development, and has been shown to function as both an oncogene and tumor suppressor during prostate carcinogenesis." (PMID 20056578, 2010).
psychosis (3 papers, 2020 to 2022). "We next examined the mRNA levels of Notch1 signalling in the mPFC, NAc, and Hip, which are psychosis-related brain regions." (PMID 35732696, 2022). "Although the Notch1 signalling pathway has been shown to play a part in the pathogenesis of some psychiatric disorders, its role in METH-induced psychosis (MIP) is still unknown." (PMID 35732696, 2022).
pulmonary atresia (3 papers, 2018 to 2022). "Genome sequencing analyses identified two pathogenic CNVs: A 138-kb deletion, including NOTCH1, was identified in a proband with TOF and pulmonary atresia, but no obvious other features of Adams–Oliver syndrome." (PMID 32037394, 2020).
renal failure (3 papers, 2019 to 2022). "Cisplatin also stimulated Notch1 cleavage and caused renal insufficiency and cell death which were reversed by DAPT, a γ‐secretase inhibitor." (PMID 30407728, 2019).
rhabdomyosarcoma (3 papers, 2017 to 2025). A rare aggressive malignant mesenchymal neoplasm arising from skeletal muscle. "Finally, high NOTCH1 expression was associated with reduced survival and poor outcome in human rhabdomyosarcoma patients (p = 0.013, log-rank statistic)." (PMID 28614716, 2017). "In addition, a high-impact mutation in NOTCH1 was confirmed in rhabdomyosarcoma." (PMID 40446009, 2025). "Real-time qPCR of primary human rhabdomyosarcoma independently confirmed that NOTCH1 was highly expressed in a majority of tumors (n = 8 of 12 samples expressed a >4-fold increase in NOTCH1 when compared with normal muscle)." (PMID 28614716, 2017). "Rhabdomyosarcoma subtypes also exhibited a trend toward worse outcome based on high NOTCH1 expression, yet these analyses failed to reach statistical significance due to small sample sizes." (PMID 28614716, 2017). "Despite these studies uncovering important roles for NOTCH1 in regulating rhabdomyosarcoma growth, roles for NOTCH1 or HEY1 in regulating stem cell programs that elevate overall numbers of TPCs was not reported." (PMID 28614716, 2017). "Gene expression analysis also uncovered a high correlation of SNAI1 and NOTCH1 transcript co-expression in human primary rhabdomyosarcoma (p < 0.0001; Pearson correlation, 0.604)." (PMID 28614716, 2017). "To extend our findings to human ERMS, we first analyzed transcript expression of NOTCH1 in primary patient tumors and uncovered that NOTCH1 was highly expressed in 60% of both human alveolar rhabdomyosarcoma (ARMS) and ERMS when compared with normal muscle controls." (PMID 28614716, 2017). "Building on our knowledge that muscle development, regeneration, and stem cell self-renewal are regulated by the NOTCH1 pathway, we undertook experiments to assess a role for NOTCH1 in regulating human rhabdomyosarcoma growth through specifically affecting TPCs." (PMID 28614716, 2017). "We also assessed whether NOTCH1 signaling was correlated with Hedgehog and canonical WNT/b-catenin signaling pathways previously shown to be associated with stemness and differentiation in rhabdomyosarcoma." (PMID 28614716, 2017). "In total, our experiments show that the NOTCH1/SNAI1 axis suppresses MEF2C expression, locking cells in a less differentiated cell state while elevating the overall self-renewal potential of rhabdomyosarcoma." (PMID 28614716, 2017).
schizophrenia (3 papers, 2015 to 2024). A major psychotic disorder characterized by abnormalities in the perception or expression of reality. "In addition, in a genome-wide molecular-network analysis, NOTCH1 was predicted to be one of the most important nodes that link genes in which genetic variants possibly involved in schizophrenia susceptibility due the presence of T. gondii seropositivity." (PMID 39199321, 2024). "Burden significance for both FLT4 and NOTCH1 was highly specific to CHD compared to an unrelated schizophrenia sample and was further confirmed by the gnomAD singleton comparison analysis." (PMID 33110418, 2020). "Quetiapine ameliorated the schizophrenia-like behaviors and decreased expression of myelin basic protein and inhibition of Notch signaling molecules, such as Notch1, Hes1, and Hes5, in the forebrain that induced by cuprizone." (PMID 26232790, 2015). "Meanwhile, the Notch4 locus has been identified as a candidate susceptibility gene for schizophrenia, and the mRNA level of Notch1 is differentially expressed in parvalbumin-immunoreactive neurons in subjects with schizophrenia." (PMID 26232790, 2015).
stomach cancer (3 papers, 2014 to 2022). "Furthermore, to explore whether Notch1 expression is associated with the metastasis of GC, the Notch1 expression levels were examined in 45 gastric tumor samples." (PMID 24932308, 2014).
Turner syndrome (3 papers, 2020 to 2024). Turner syndrome is a chromosomal disorder associated with the complete or partial absence of an X chromosome. "Other syndromes seen in our patients include DiGeorge syndrome (OMIM# 188400), Cat-eye syndrome (OMIM# 115470), mosaic Turner syndrome, and Adams–Oliver syndrome-5 (OMIM# 616028) confirmed by a pathogenic variant in NOTCH1." (PMID 33578785, 2021).
vascular malformation (3 papers, 2015 to 2021). A non-neoplastic disorder that is the result of defects of vascular morphogenesis. "Using both immunohistochemistry on microarrays and western blot analysis, they found that Notch-1 expression was detectable in control vessels, and discovered a significant decrease of Notch 1 expression in vascular malformations." (PMID 33837504, 2021). "NOTCH1–4 proteins are variably expressed in a range of these extracranial vascular malformations involving lymphatic, venous and arterial vessels." (PMID 30573741, 2018). "Using both immunohistochemistry on microarrays and western blot analysis, we have found that Notch-1 expression was detectable in control vessels, and discovered a significant decrease of Notch 1 expression in vascular malformations." (PMID 25846406, 2015). "Notch 1 and 4 have been detected in human and mutant mice vascular malformations respectively." (PMID 25846406, 2015). "Collectively, these data suggest a link between the misexpression of Notch family members and NOTCH1 and NOTCH4 activation in human extracranial vascular malformations of all types." (PMID 30573741, 2018).
verrucous carcinoma (3 papers, 2021 to 2023). A well differentiated squamous cell carcinoma characterized by a papillary growth pattern, acanthosis, mild cytologic atypia, and pushing tumor margins. "In one study, it was reported that ALDH1 and Notch1 were uncommonly detected in verrucous carcinoma, whereas in another, the significantly increased expression of ALDH1 and SOX2 is associated with verrucous carcinoma." (PMID 37303447, 2023). "All verrucous carcinomas showed negative/weak ALDH1 immunoexpression, and strong Notch1 immunopositivity was observed in three tumors (42.9%)." (PMID 33854547, 2021).
acute pancreatitis (2 papers, 2012 to 2016). An acute inflammatory process that leads to necrosis of the pancreatic parenchyma. "Recent findings indicate Notch1 plays a role in pancreatic homeostasis, since loss of Notch1 in pancreatic epithelium results in impaired acinar regeneration following acute pancreatitis." (PMID 23284900, 2012). "Similarly, mice deficient for Notch1 in pancreatic epithelium also display impaired acinar regeneration following acute pancreatitis." (PMID 23284900, 2012). "Notch1-dependent β-catenin transcriptional activity is inhibited by treatment with the γ-secretase inhibitor dibenzazepine (DBZ) during acute pancreatitis." (PMID 27203385, 2016). "Such hypothesis is further supported by the upregulation of CD24 during acute pancreatitis in concomitance to inhibition of Notch1-dependent β-catenin transcriptional activity by DBZ treatment." (PMID 27203385, 2016). "We further investigated the effect of Notch1 deletion in the Elastase1-CreERT2;LSL-K-rasG12D model following acute pancreatitis." (PMID 23284900, 2012). "Similar grades of pancreatic pathology were noted in Elastase1-CreERT2;LSL-K-rasG12D;Notch1lox/lox (n = 6) mice, indicating Notch1 deletion does not accelerate PanIN formation following acute pancreatitis." (PMID 23284900, 2012).
adult T cell leukemia (2 papers, 2022 to 2023). "We aimed to determine the function of NOTCH1 expression and the effects of GSI on adult T-cell leukemia/lymphoma (ATL) caused by long-term human T-cell leukemia virus type I (HTLV-1) infection." (PMID 36243685, 2022).
alcohol steatohepatitis (2 papers, 2021). "Conditional NOTCH1 deficiency in myeloid cells attenuated hepatic macrophage M1-like activation and inflammation in murine alcoholic steatohepatitis and markedly reduced lethality following endotoxin-mediated fulminant hepatitis." (PMID 33868313, 2021). "Pharmacologic (DAPT) or genetic inhibition (myeloid-specific Notch1 KO mice) of Notch in mouse models of alcoholic steatohepatitis or galactosamine/LPS-induced fulminant hepatitis." (PMID 33912195, 2021). "In murine models of alcohol steatohepatitis, MoMFs are recruited to the liver in a NOTCH1-mediated mechanism with subsequent M1-like macrophage activation." (PMID 33868313, 2021).
amyotrophic lateral sclerosis (2 papers, 2021 to 2023). Amyotrophic lateral sclerosis (ALS) is a neurodegenerative disease characterized by progressive muscular paralysis reflecting degeneration of motor neurons in the primary motor cortex, corticospinal tracts, brainstem and spinal cord. "Strikingly, NOTCH1 signal transduction is reactivated in reactive astrocyte populations after intra-cerebral hemorrhage, in stroke and in several neuro-inflammatory conditions such as amyotrophic lateral sclerosis (ALS), MS and experimental auto-immune encephalomyelitis (EAE)." (PMID 37936690, 2023).
angiomyolipoma (2 papers, 2017 to 2025). A neoplasm with perivascular epithelioid cell differentiation often associated with tuberous sclerosis. "Our data imply that angiomyolipoma cells do not achieve terminal differentiation and remain as neural stem-like cells or progenitors; therefore, we explore the possibility of oscillatory Notch1 signaling gene expression as an underlying mechanism blocking angiomyolipoma cell differentiation." (PMID 29184052, 2017). "Recent findings showed that angiomyolipoma (AML) tumor cell-derived EVs contain NOTCH1 esRNAs, leading to constitutive activation of the Notch1 pathway." (PMID 40182121, 2025). "Given that the suppression of Rheb correlated with the suppression of Notch1 during neuronal differentiation of angiomyolipoma cells, we conclude that inhibition of the Rheb-Notch-Rheb regulatory loop is required for this process." (PMID 29184052, 2017). "We used chromatin immunoprecipitation qPCR (ChIP-qPCR) to examine the binding of Notch1 to the promoter of Rheb and Hes1 (as a positive control) in angiomyolipoma cells in Dulbecco’s modified Eagle’s medium (DMEM) to identify which sites are functionally important and correspond to true NREs." (PMID 29184052, 2017). "Since oscillation of Notch maintains multipotent NSCs, we propose that the Rheb-Notch-Rheb loop, controlled by fluctuations in the binding of Notch1 to Rheb-activating and Hes1-activating NREs, contributes to maintaining multipotent properties of angiomyolipoma cells." (PMID 29184052, 2017). "To determine whether hyperactivation of Rheb and Notch prevents neuronal differentiation, we used short hairpin RNA (shRNA) to deplete angiomyolipoma cells of Rheb46 or Notch1." (PMID 29184052, 2017). "We propose that decreased binding of Notch1 to NREs may lead to suppression of Rheb and Hes1 expression and decreased oscillation, leading to sustained, low level of Rheb and Hes1, followed by neuronal differentiation of angiomyolipoma cells." (PMID 29184052, 2017). "However, both angiomyolipoma cell lines 621–101 and CRL4004 used in this work have multiple common features such as mTORC1 hyperactivation, differentiation abnormalities, binding of Notch1 to the RHEB and HES1 promoters, and oscillation of RHEB and HES1 mRNAs and proteins." (PMID 29184052, 2017).
aplasia cutis congenita (2 papers, 2024 to 2025). Aplasia cutis congenita (ACC) is a rare skin disorder characterized by localized absence of skin that is usually located on the scalp but can occur anywhere on the body including the face, trunk and extremities. "Cutis aplasia congenita, cutis marmorata, and the digit anomalies observed in our cohort are known features of AOS and have been observed specifically in the context of NOTCH1 variants." (PMID 38778082, 2024).
aplastic anemia (2 papers, 2020 to 2023). Anemia resulting from bone marrow failure (aplastic or hypoplastic bone marrow). "The present study aimed to assess the gene expressions of NOTCH-1 and T helper cell transcription factors in the acquired aplastic anemia patients." (PMID 37980558, 2023). "In aplastic anemia patients, the promoter of TBX21 (T-bet coding gene) binds to NICD1 (the active form of Notch1) to regulate Th1-mediated immune response." (PMID 33224898, 2020).
arteriovenous malformations (2 papers, 2015). "Furthermore, Notch1+/−; Notch3−/− mice displayed retinal AVMs, pointing to a key role for pericytes in normal vascular function and indicating that pericyte dysfunction due to Notch deficiency contributes to arteriovenous malformations." (PMID 26563570, 2015). "We have demonstrated that Notch 3 and 4, and not Notch 1, were highly increased in human arteriovenous malformations." (PMID 25846406, 2015).
brain glioma (2 papers, 2017 to 2022). A malignant glioma that involves the brain. "Isoliquiritigenin, isolated from licorice, has been found to be a potent stimulator of cell differentiation and has potential application for treating human brain glioma by inhibiting proliferation and blocking angiogenic through Notch1 and Akt signaling pathway, respectively." (PMID 35140796, 2022).
breast ductal carcinoma (2 papers, 2016 to 2021). "Abnormal expressions of Notch-1, Notch-4 or Jagged-1 are common in breast ductal carcinoma and lobular carcinoma." (PMID 34872446, 2021). "We also can design new therapeutic agents targeting NOTCH1 expression for inhibition of metastasis in ductal breast carcinoma." (PMID 28330128, 2016).
CADASIL syndrome (2 papers, 2013 to 2024). "Association of Notch3 mutations and Notch1 inactivating mutations with CADASIL syndrome and severe heart disorders, respectively, strongly support this hypothesis." (PMID 23531541, 2013).
cervical (2 papers, 2018 to 2020). "The elevated IDO1 expression in cervical tumorsphere cells was inhibited by the inactivation of Notch1 activity by the knockdown of Notch1 or the treatment of a γ-secretase inhibitor." (PMID 32545442, 2020).
cervical dysplasia (2 papers, 2018 to 2021). "NOTCH1, a master cell fate regulator that has a complex role in cervical dysplasia and cancers was quantified." (PMID 34944802, 2021). "NOTCH1, though it decreased at the transcript and protein level in 16E6E7 HFKs and in cancer cells, exhibited high expression in cervical dysplasia and a positive LASSO coefficient." (PMID 34944802, 2021). "For example, the increase in NOTCH1 mRNA in cervical dysplasia may be a result of another HPV gene." (PMID 34944802, 2021). "We aimed to investigate the role of NOTCH1 and NUMB expression and their localization in cervical intraepithelial neoplasia (CIN) and ICC samples." (PMID 29721172, 2018). "Unlike CEBPD, SLPI, KRT16, and RPS29, NOTCH1 expression in these cell lines did not match the increase seen in cervical dysplasia and cancer samples in silico." (PMID 34944802, 2021).
cervical tumors (2 papers, 2010 to 2016). "We thus propose RhoC to be a downstream effector of Notch1 in cervical tumour progression." (PMID 19953094, 2010). "As both Notch1 and RhoC are involved in tumour progression and metastasis, we investigated whether the two signalling molecules regulate similar functions during cervical tumour progression." (PMID 19953094, 2010).
chronic myelomonocytic leukaemia (2 papers, 2015 to 2023). "PTPN11mut was more common in myelomonocytic and monocytic leukemia, and was more likely to co‐mutate with KRAS, KMT2C, NRAS, U2AF1, NOTCH1, IKZF1, and USH2A mutations than PTPN11wt." (PMID 37937729, 2023). "Contrary to these observations, inactivation of Notch1 in mouse HSCs induced chronic myelomonocytic leukaemia (CMML) and Notch1 here has been suggested to have tumour suppressor roles." (PMID 25711903, 2015).
cleft palate (2 papers, 2019 to 2021). Cleft palate is a fissure type embryopathy that affects the soft and hard palate to varying degrees. "This comprehensive analysis revealed decreases in gene expressions associated with lung development; Foxa2, Notch1, Foxp2, Nkx2.1, and intestine development; Cdx2, Foxf2, Foxl1, and skeletal development; Hoxd12, Hoxd13, Scx, Brachyury, and cleft palate; Foxf2." (PMID 34671097, 2021).
cognitive decline (2 papers, 2019 to 2025). "Moreover, baicalein exerts a neuroprotective effect against cognitive decline through the SIRT1-mediated Notch1 pathway, which in turn improves angiogenesis and suppresses neuroinflammation." (PMID 40290868, 2025).
deafness (2 papers, 2014 to 2019). An inherited or acquired condition characterized by the complete loss of the ability to hear from one or both ears. "Notch1 is the primary Notch receptor expressed in the mouse inner ear, and activation of Notch1 in developing auditory HCs causes profound deafness, while deletion of Notch1 leads to limited mitotic HC generation." (PMID 31791390, 2019). "Activation of Notch1 in developing auditory hair cells causes profound deafness." (PMID 25264928, 2014).